PHGDH (phosphoglycerate dehydrogenase)
Diseases named in the same sentence as PHGDH in open-access papers (continued):
Sharing a sentence is not in itself a finding about the gene and the disease.
breast tumors (11 papers, 2011 to 2025). "Meanwhile, transcriptomic data analysis from the TCGA and GTEx projects confirmed that PHGDH expression is markedly downregulated in breast tumor tissues compared to the surrounding normal tissue." (PMID 41333208, 2025). "Within primary breast tumors, intratumor PHGDH expression is evident, and a low level of PHGDH expression is a marker of metastasis in patients." (PMID 38945960, 2024). "Compared to control cells, ASS1 knockout greatly enhanced the growth of xenograft breast tumors, whereas PHGDH knockout largely inhibited the growth of xenograft breast tumors." (PMID 38710705, 2024). "Previous work has shown that PHGDH is required for breast tumor initiation and growth in MCF10DCIS.com and MDA-MB-468 in vivo models, which is ostensibly in contrast with our results." (PMID 24318446, 2013). "While recent studies showed the requirement of PHGDH in human breast tumor initiation, the role of PHGDH in established breast tumors is not fully understood." (PMID 24318446, 2013). "Importantly, PHGDH amplifications and an enhanced ability to synthesize serine have previously been reported in basal breast tumors." (PMID 35045283, 2022). "However, PHGDH is dispensable for breast tumor maintenance and growth in vivo, suggesting that requirement of PHGDH is context-dependent." (PMID 24318446, 2013). "PHGDH has recently been recognized to be highly expressed in primary breast tumors." (PMID 21437235, 2011). "Notably, PHGDH inhibitors effectively suppress the growth of IDH2-overexpressing breast tumors in pre-clinical models, indicating that targeting PHGDH could be a promising approach for TNBC with IDH2 overexpression." (PMID 39973065, 2025). "PHGDH was also among the top-scoring genes, and PSPH expression was also reduced in luminal breast tumors." (PMID 35045283, 2022). "Interestingly, PHGDH overexpression is associated with certain breast subtypes, and reduction of PHGDH reduced breast tumors growth, while ectopic PHGDH expression in mammary epithelial cells induced phenotypic alterations that may predispose cells to transformation." (PMID 32825455, 2020). "Furthermore, the weight of breast tumor xenografts in derived from ASS1 knockout cells significantly increased, but the weight of breast tumor xenografts derived from PHGDH knockout cells decreased greatly relative to that of control cells." (PMID 38710705, 2024). "Among 82 human breast tumor samples assessed in an immunohistochemical assay (not discussed in this review) PHGDH protein levels significantly correlated with estrogen receptor-negative status." (PMID 25574168, 2014). "Analysis of the proteome of human breast tumors also revealed very low levels of PHGDH and PSAT1 (but not PSPH) protein in luminal breast tumors." (PMID 35045283, 2022).
multiple myeloma (11 papers, 2017 to 2024). "Serine starvation consistently enhanced bortezomib cytotoxicity, and the rate-limiting enzyme of the serine synthesis process, PHGDH, is upregulated in many Bortezomib-resistant myeloma cells, which underline that serine metabolism plays an important role in the treatment of myeloma cells." (PMID 37190313, 2023). "We then evaluate the effects of manipulating PHGDH expression on serine production, megakaryopoiesis, and thrombopoiesis by generating APR1 myeloma cells with PHGDH ectopic expression or knockdown." (PMID 37055385, 2023). "In multiple myeloma, cancer cells occasionally gain bortezomib resistance, enhancing serine biosynthesis through PHGDH and ultimately leading to increased antioxidant capacity across different multiple myeloma cell lines." (PMID 35011702, 2022). "All the tested myeloma cell lines expressed PHGDH and were sensitive to doses of NCT-503 that were tolerated by peripheral blood mononuclear cells isolated from healthy donors." (PMID 33397437, 2021). "NCT-503, another PHGDH inhibitor, is under pre-clinical investigation in multiple myeloma." (PMID 33652666, 2021). "Importantly, in CD138+ cells of clinically bortezomib refractory multiple myeloma patients, PHGDH expression was also markedly increased." (PMID 28855983, 2017). "Two different PHGDH inhibitors, CBR5884 and NCT-503, were tested against human myeloma cell lines, primary MM cells from patients, and peripheral blood mononuclear cells isolated from healthy donors." (PMID 33397437, 2021). "For example, phosphoglycerate dehydrogenase (PHGDH), the rate-limiting enzyme of de novo serine biosynthesis, is commonly overexpressed in malignant tumors and was recently shown to promote bortezomib resistance of multiple myeloma cells." (PMID 33182817, 2020). "Moreover, our results link both serine synthesis pathway activity and expression of 3-phosphoglycerate dehydrogenase (PHGDH), which catalyzes the rate-limiting step of serine synthesis, to bortezomib resistance across different BTZ-resistant multiple myeloma cell lines." (PMID 28855983, 2017).
acute myeloid leukemia (10 papers, 2017 to 2025). Acute myeloid leukemia (AML) is a group of neoplasms arising from precursor cells committed to the myeloid cell-line differentiation. "Nevertheless, a recent study found human PHGDH to be able to catalyze the NADH-dependent reduction of α-KG to D-2-hydroxyglutarate, an oncometabolite associated with brain cancer and acute myeloid leukemia." (PMID 29262655, 2017). "NSUN2 also methylates mRNAs, where m5C stabilizes transcripts encoding key metabolic enzymes, including PHGDH and SHMT2, which are essential for serine/glycine biosynthesis and are implicated in acute myeloid leukemia (AML) progression and leukemic stem cell (LSC) self-renewal." (PMID 40973767, 2025). "In acute myeloid leukemia (AML), NSUN2 stabilizes PHGDH and SHMT2 mRNA and upregulates their expression by regulating m5C modification." (PMID 41462962, 2025).
neuroblastoma (9 papers, 2021 to 2026). Neuroblastoma (NB) is the most common solid, extracranial childhood tumor. "PHGDH expression was enhanced in neuroblastoma cells with ASS1 deficiency treated with arginine deiminase, with a concomitant enrichment of intracellular serine and glycine and downregulation of the Warburg effect." (PMID 36319669, 2022). "We examined the correlations between MYCN status, MYCN expression, and PHGDH expression in 94 samples with high-risk neuroblastoma, in the TARGET cohort; the expression of the genes in all samples was examined, that is, for cases with and without 11q LOH." (PMID 36319669, 2022). "Thus, a high PHGDH expression is associated with two important neuroblastoma subgroups: those with MYCN amplification and those with 11q LOH and poor prognosis." (PMID 36319669, 2022). "Preclinical targeting demonstrates that NCT-503 suppresses Ewing sarcoma progression, while genetic ablation confirms PHGDH as a survival dependency in neuroblastoma." (PMID 41486146, 2026). "CBS, AHCY and PHGDH expression was also elevated in mass spectrometry-based global proteomes from MYCN-amplified neuroblastoma tumors." (PMID 35484422, 2022). "We conducted knockdown assays using siRNA on neuroblastoma cell lines to identify the significance of PHGDH expression in aggressive neuroblastoma cells." (PMID 36319669, 2022). "The attenuated effects of PHGDH inhibitors by NAC also demonstrate that PHGDH contributes to oxidative stress reduction in neuroblastoma through glutathione production and that PHGDH inhibitors block this function." (PMID 36319669, 2022). "They reported that NCT-503 slowed proliferation of neuroblastoma in vivo but had a limited effect in killing cells; they concluded that PHGDH inhibition has limited potential as a treatment option for neuroblastoma." (PMID 36319669, 2022). "Most relevant here, up‐regulation of the SGOC pathway correlated with MYCN amplification in neuroblastoma, and MYCN sensitized neuroblastoma cells to pharmacological inhibition of one of its components, phosphoglycerate dehydrogenase." (PMID 36214609, 2022). "We proposed a candidate treatment that is expected to be particularly effective for neuroblastomas with enhanced PHGDH expression, i.e., with MYCN amplifications and 11q LOH and poor prognosis." (PMID 36319669, 2022). "NAC partially reduced the cytotoxicity of PHGDH inhibitors on neuroblastoma cell lines in vitro, indicating that PHGDH works for oxidative stress reduction in neuroblastoma." (PMID 36319669, 2022). "Since PHGDH was reported to have a protective role against oxidative stress through glutathione production, the interaction between N-acetylcysteine (NAC), a radical scavenger, and PHGDH inhibition in neuroblastoma was examined." (PMID 36319669, 2022). "To determine the cellular responses with PHGDH inhibition and arginine depletion in neuroblastoma cells, we conducted transcriptome analysis using post-dose cell lines under the same condition as those in the metabolome analysis." (PMID 36319669, 2022). "Since PHGDH catalyses the rate-limiting step in serine synthesis, we performed metabolic analyses in neuroblastoma cells to investigate the effects of NCT-503 treatment on cellular metabolism." (PMID 34192988, 2021). "By random observation, we noticed that NCT-503 treatment also attenuated proliferation of neuroblastoma cells expressing low PHGDH levels." (PMID 34192988, 2021). "The small molecule inhibitor, NCT-503, not only targets PHGDH, the rate limiting enzyme in de novo serine synthesis, but also induces a remodelling of glucose-derived carbon flow into the TCA cycle independently of PHGDH expression in neuroblastoma cells." (PMID 34192988, 2021). "In particular, attenuating glutathione production by PHGDH inhibitors may enhance the effect of various chemotherapies by attenuating the resistance of neuroblastoma cells to oxidative stress." (PMID 36319669, 2022).
neuroblastoma (continued). "PHGDH inhibition suppressed neuroblastoma cell proliferation in vitro and in vivo, indicating that the inhibition of serine metabolism by PHGDH inhibitors is a therapeutic alternative for neuroblastoma." (PMID 36319669, 2022). "Phosphoglycerate dehydrogenase (PHGDH) is a suitable marker for risk stratification, as it is highly upregulated in high-risk MYCN-amplified neuroblastoma; however, its inhibition by small molecule inhibitors antagonized chemotherapy efficiency in patient-derived xenografts in mice." (PMID 35008547, 2021). "Our data obtained with NCT-503-treated PHGDH knockout neuroblastoma cell clones demonstrates that the reduced incorporation of glucose-derived carbons into citrate is completely independent of the expression of PHGDH itself and, thus, due to an off-target effect of NCT-503." (PMID 34192988, 2021). "Similarly, PHGDH inhibition synergized with ADI-PEG 20 in neuroblastoma cell lines and xenografts." (PMID 40813699, 2025). "MYCN can also drive transcription of ATF4 in neuroblastoma cells, and it was demostrated that targeting either MYCN or ATF4 leads to decreased expression levels of PHGDH, PSAT1, SHMT2, MTHFD2, and MTHFD1L." (PMID 37949226, 2023). "Our findings demonstrated the excellent combination effects of PHGDH inhibitor and ADI-PEG20 for neuroblastoma in vivo." (PMID 36319669, 2022). "To investigate the combinational treatment of PHGDH inhibition and arginine depletion in neuroblastomas, we confirmed ASS1 expression levels in neuroblastomas and their correlation with PHGDH expression levels." (PMID 36319669, 2022). "Here we describe an off-target effect of NCT-503 in neuroblastoma cell lines expressing divergent phosphoglycerate dehydrogenase (PHGDH) levels and single-cell clones with CRISPR-Cas9-directed PHGDH knockout or their respective wildtype controls." (PMID 34192988, 2021). "Although survival extension in xenograft models supports target engagement, PHGDH inhibition in MYCN-amplified neuroblastoma models primarily induces cytostatic effects rather than cytotoxicity, and tumors rapidly develop resistance through metabolic rewiring." (PMID 41486146, 2026). "Similarly, MYC-family oncoproteins directly occupy the PHGDH promoter, driving overexpression in Group 3 medulloblastoma and MYCN-amplified neuroblastoma." (PMID 41486146, 2026). "We conclude that NCT-503 triggers metabolic remodelling in neuroblastoma cells, independent of PHGDH expression." (PMID 34192988, 2021). "Therefore, PHGDH expression is also important in neuroblastoma without MYCN amplification as a prognostic factor as well as a therapeutic target." (PMID 36319669, 2022). "Although PHGDH was reported to be essential for intracellular serine biosynthetic pathway, the administration of PHGDH inhibitors did not decrease the serine or glycine levels in neuroblastoma cells." (PMID 36319669, 2022).
microcephaly (8 papers, 2014 to 2023). A congenital or acquired developmental disorder in which the circumference of the head is smaller than normal for the person's age and sex. "Humans with mutated PHGDH have lower levels of free L-serine in the plasma and in cerebrospinal fluid and exhibit severe neurological symptoms, including congenital microcephaly, psychomotor retardation, and intractable seizures." (PMID 37999510, 2023). "Of note, PHGDH deficiency was linked to a neurological disease defined by congenital microcephaly, psychomotor retardation, and seizures, as well as neuropathy." (PMID 33458610, 2021). "PHGDH deficiency in humans causes neuropathy and postnatal microcephaly." (PMID 25197619, 2014). "Severe neurological abnormalities in PHGDH knockout mice include congenital microcephaly and psychomotor impairment." (PMID 37628788, 2023). "Mutations PHGDH, PSPH, and PSAT1 in the serine-glycine pathway have been associated with Neu-Laxova syndrome, which is characterized by a spectrum of phenotypes that vary in expression but usually manifests by perinatal lethality, microcephaly, skeletal, and skin anomalies." (PMID 36737727, 2023). "In knockout mice in whom 3-phosphoglycerate dehydrogenase (PHGDH) in the L-serine synthetic pathway is inactivated, abnormal brain morphogenesis, including microcephaly and absence of specific regions, and brain dysfunction occurs." (PMID 25197619, 2014).
Ewing sarcoma (7 papers, 2020 to 2026). A small round cell tumor that lacks morphologic, immunohistochemical, and electron microscopic evidence of neuroectodermal differentiation. "Phosphoglycerate dehydrogenase (PHGDH) is highly expressed in Ewing’s sarcoma and is associated with poor patient survival." (PMID 34925434, 2021). "This dependency is exploited therapeutically, as PHGDH inhibition synergizes with NAMPT inhibition in Ewing sarcoma and with tyrosine kinase inhibitors in HCC to overcome chemoresistance." (PMID 41486146, 2026). "The Menin-MLL complex directly occupies the PHGDH promoter in Ewing sarcoma, diverting glycolytic flux toward serine/glycine biosynthesis." (PMID 41486146, 2026). "ATF4 is a master regulator of transcription for amino acid metabolism and stress responses and has been shown to activate the SSP in various solid tumors that lack amplification of the PHGDH locus, such as Ewing sarcoma." (PMID 39336822, 2024). "Furthermore, inhibition of serine synthesis at phosphoglycerate dehydrogenase in Ewing sarcoma cells significantly inhibits cell proliferation in the absence of exogenous serine and glycine, in line with a critical role of one-carbon metabolism in supporting Ewing sarcoma cell growth." (PMID 40698729, 2025). "KDM4B-mediated H3K36me3 erasure suppresses PHGDH activity, whereas Menin-MLL/TrxG complexes deposit activating H3K4me3 in Ewing sarcoma to prime SSP genes for nucleotide biosynthesis." (PMID 41486146, 2026). "Furthermore, PHGDH, which catalyzes the rate-limiting step of the SSP, is overexpressed in Ewing sarcoma and promotes Ewing sarcoma cell proliferation, survival, and tumor growth." (PMID 39336822, 2024).
osteosarcoma (7 papers, 2014 to 2026). A usually aggressive malignant bone-forming mesenchymal neoplasm, predominantly affecting adolescents and young adults. "In osteosarcoma cells, autophagy is induced by G9a suppression, which then causes down-regulation of serine-glycine biosynthetic genes PHGDH and SHMT, suggesting that a G9a-dependent epigenetic program in the control of cell metabolism sustains cancer growth and survival." (PMID 25027955, 2014). "RFWD3-driven PHGDH degradation redirects flux toward NAD+/TCA cycle-dependent nucleotide synthesis in osteosarcoma." (PMID 41486146, 2026). "In summary, lomitapide disrupts the interaction between RFWD3 and PHGDH, thereby enhancing cisplatin sensitivity in osteosarcoma." (PMID 40019400, 2025). "In summary, this study identifies the RFWD3/PHGDH axis as a pivotal regulator of DDP resistance in osteosarcoma." (PMID 40019400, 2025). "Collectively, these findings underscore the pivotal role of PHGDH in DDP resistance in osteosarcoma." (PMID 40019400, 2025). "This modification impacts PHGDH's stability, thereby influencing metabolic pathways critical for osteosarcoma chemoresistance." (PMID 40019400, 2025). "Here, PHGDH inhibition in combination with mTORC1 signaling modulation for the treatment of osteosarcoma was evaluated." (PMID 39934141, 2025). "For example, inhibition of PHGDH (NCT503) in osteosarcoma increased LAT1/CD98hc expression and augmented intracellular BCAAs with consequent mTORC1 activation and increased survival." (PMID 37880212, 2023). "Identifying a therapeutic combination for PHGDH-high cancers offers preclinical justification for a dual metabolism-based combination therapy for osteosarcoma." (PMID 33503424, 2021). "The inhibitory capacity of NCT-503 on PHGDH has been reported and was assessed in osteosarcoma cell lines using a PHGDH activity assay." (PMID 33503424, 2021). "This work, therefore, provides the preclinical rationale for testing a metabolic combination therapy targeting PHGDH and mTORC1 biology as a replacement for high-dose methotrexate in osteosarcoma." (PMID 33503424, 2021). "Given the high levels of de novo serine biosynthesis in PHGDH-high osteosarcoma, the basal flux of glucose would likely be through the serine synthetic pathway, necessitating alternate mitochondrial fuel sources, such as fatty acids." (PMID 33503424, 2021). "Here, the rate-limiting enzyme in the biosynthesis of serine from glucose, 3-phosphoglycerate dehydrogenase (PHGDH), is examined, and an inverse correlation between PHGDH expression and relapse-free and overall survival in osteosarcoma patients is found." (PMID 33503424, 2021). "With PHGDH inhibition, the glycolytic rate in osteosarcoma cell lines was increased, demonstrating that, instead of entering de novo serine biosynthesis through 3PG, glucose was shunted through glycolytic intermediates." (PMID 33503424, 2021). "This study demonstrates that high levels of PHGDH correlated with poor overall relapse-free and poor overall survival outcomes in patients with osteosarcoma." (PMID 33503424, 2021). "This demonstrated that high PHGDH expression was correlated with osteosarcomas with poorer outcomes." (PMID 33503424, 2021). "The independent metabolomics and [U-13C] glucose tracings conducted in osteosarcoma cell lines demonstrated that PHGDH inhibition consistently modified these pathways." (PMID 33503424, 2021). "High levels of PHGDH are inversely correlated with survival in osteosarcoma patients, with inhibition of the enzyme effective in blocking proliferation of osteosarcoma cells." (PMID 34319488, 2021). "KMT2A-mediated H3K4 methylation promoting PHGDH expression and lung metastasis in osteosarcoma." (PMID 41486146, 2026).